PTPRF (protein tyrosine phosphatase receptor type F)
Diseases named in the same sentence as PTPRF in open-access papers (continued):
Sharing a sentence is not in itself a finding about the gene and the disease.
Nephropathy (1 paper, 2022). A nonspecific term referring to disease or damage of the kidneys. "Since DR is usually accompanied by other diabetic complications, such as nephropathy and neuropathy, the mutant genes, such as PTPRF and CRELD2 were linked with more than one type of complication, including DR." (PMID 36035153, 2022).
neuroblastoma (1 paper, 2021). Neuroblastoma (NB) is the most common solid, extracranial childhood tumor. "PTPRF gene maps at 1p34, within a region frequently deleted in high-risk neuroblastoma." (PMID 34957126, 2021). "Whether PTPRS or PTPRF may directly regulate the tyrosine phosphorylation of Trk receptors or other specific substrates in neuroblastoma cells, deserves experimental analysis." (PMID 34957126, 2021).
opioid use disorder (1 paper, 2023). A substance-related disorder that involves the recurring use of opioids despite negative consequences. "Intriguingly, PTPRF has been recently associated with problematic prescription opioid use and opioid use disorder, as well as smoking initiation/cessation, cognition, and educational attainment." (PMID 37173343, 2023). "We also detected associations near XKR6 and AFF3, which have been recently implicated in externalizing psychopathology, and PTPRF and KDM4A, recently implicated in problematic opioid use and opioid use disorder." (PMID 37173343, 2023).
Stroke (1 paper, 2022). Sudden impairment of blood flow to a part of the brain due to occlusion or rupture of an artery to the brain. "Importantly, GWAS have associated variants of several of the gene targets of miR-24-3p;FAF1, GATA3, MMP14, NOS3 and PTPRF with stroke." (PMID 36613546, 2022).
tumor (20 papers, 2003 to 2025). "Fascin actin-bundling protein 1 (FSCN1) and protein tyrosine phosphatase receptor type F (PTPRF) promote tumor progression in LUSC." (PMID 38841622, 2024). "Recently, PTPRF/LAR has been shown to have both the tumor suppressive and oncogenic properties, and its expression is altered in cancer." (PMID 34654889, 2021). "Tumor samples from high-risk group A showed a higher mean overall IHC score for Anti-MSX1, Anti-CD271, Anti-ERRFI1, Anti-PTPRF, Anti-TNFRSF21, Anti-TNFRSF12a, and Anti-IGFBP2, but without significance." (PMID 30641895, 2019). "Using a loss-of-function screening of phosphatome to identify genes suppressing tumor initiation in HCC, PTPRF was characterized as one of the top-scoring tumor suppressor candidates." (PMID 29558404, 2018). "PTPRF suppressed cell proliferation and colony formation in Huh7 and SK-Hep1 cells and inhibited HepG2 xenograft tumor growth in nude mice." (PMID 29558404, 2018). "The phosphatase activity of PTPRF is required for its tumor suppressor function." (PMID 29558404, 2018). "In vitro and in vivo studies indicated that the expression of mir-24-3p enhanced tumor growth, invasion into local tissues, metastasis to lung tissues and decreased overall mouse survival by direct targeting PTPN0 and PTPRF and therefore downregulating phosphorylation levels of EGFR." (PMID 29560116, 2018).
cancer (16 papers, 2010 to 2025). A tumor composed of atypical neoplastic, often pleomorphic cells that invade other tissues. "The levels of several mRNAs that code for surface proteins with roles in cancer were similarly upregulated, including ALK, PTPRM, PTPRF, PTPRK, and SVEP1." (PMID 39335212, 2024). "In conclusion, six core genes including COL3A1, EEF2, FN1, PTPRF SDC2, and RAC1, and several cancer-related metabolic processes, signaling pathways, and overall survival rate of patients were identified in BM PCa." (PMID 34229299, 2021). "We computationally predicted PTPRF, PRKAR2B, MAP4K3, and RICTOR to be responsible for the cancer phenotype, and each of them was experimentally validated by means of cell death or migration assay." (PMID 26336805, 2015). "The result showed that, CDH1, VEGFA, PTPRF and CLDN7 were up-regulated in six cancer samples, and MMP2 was down-regulated in ten cancer samples, suggested that these genes, especially MMP2, were dysregualted in most UCB samples." (PMID 24622401, 2014). "The signaling landscape that accompanies Ephexin3 in various cancer types included the tyrosine kinase receptor MET and the tyrosine phosphatase receptor PTPRF, the serine/threonine kinases MARK2 and PAK6, the Rho GTPases RHOD, RHOF and RAC1, and the cytoskeletal regulator DIAHP1." (PMID 38003617, 2023). "In addition, we observed that PTPRF was co-amplified or co-deleted with PTPRK and PTPN3 in various cancers." (PMID 36341348, 2022). "Other SRRM4 target genes such as PTPRF and PTK2, have known functions in regulating cell proliferation or apoptosis, suggesting that these genes may enable cancer cell to gain growth and survival advantages under chemo- or hormonal therapies." (PMID 28978002, 2017).
infection (2 papers, 2017 to 2025). The state of being infected such as from the introduction of a foreign agent such as serum, vaccine, antigenic substance or organism. "We examined the effect of wild-type or early-region gene-mutated adenovirus [E1B-55k-(dl1520), E4orf3-(pm4150), E4orf6-(pm4154), E4orf3-/E4orf6-(pm4155)] infection on ALCAM, EPHA2 and PTPRF." (PMID 28631589, 2017).
psychiatric disorder (2 papers, 2019 to 2025). A disorder characterized by behavioral and/or psychological abnormalities, often accompanied by physical symptoms. "In the present study, we used rare missense variants identified in individuals diagnosed with psychiatric disorders and controls to investigate the biological effects that might underlie the genetic association of PTPRF/LAR with psychiatric disorders." (PMID 40502755, 2025).
PTPRF also shares sentences with these, for which no sentence is quoted: brain disorder (2 papers); metastatic disease (2); neurological disorders (2); thyroid cancer (2); acute megakaryoblastic leukemia (1); adenoma (1); allergies (1); Anxiety (1); astrocytoma (1); autism (1); autism spectrum disorder (1); bipolar disorder (1); cardiomyopathy (1); cardiovascular disease (1); emphysema (1); endometrial cancer (1); follicular carcinomas (1); glioblastoma (1); head and neck squamous cell carcinoma (1); irritable bowel syndrome (1); lymphoma (1); macroglossia (1); metabolic disorders (1); metabolic syndrome (1); migraine (1); neurodegenerative disease (1); neuropathy (1); Obesity (1); papillary carcinoma (1); Parkinson disease (1).
A further 6 diseases each share a sentence with PTPRF in 1 paper.